ERI1 (exoribonuclease 1)
Description:
RNA exonuclease that binds to the 3'-end of histone mRNAs and degrades them, suggesting that it plays an essential role in histone mRNA decay after replication. A 2' and 3'-hydroxyl groups at the last nucleotide of the histone 3'-end is required for efficient 3'-end histone mRNA exonuclease activity and degradation of RNA substrates. Also able to degrade the 3'-overhangs of short interfering RNAs (siRNAs) in vitro, suggesting a possible role as regulator of RNA interference (RNAi). Required for binding the 5'-ACCCA-3' sequence present in stem-loop structure. Able to bind other mRNAs. Required for 5.8S rRNA 3'-end processing. Also binds to 5.8s ribosomal RNA (By similarity). Binds with high affinity to the stem-loop structure of replication-dependent histone pre-mRNAs. In vitro, does not have sequence specificity. In vitro, has weak DNA exonuclease activity. In vitro, shows biphasic kinetics such that there is rapid hydrolysis of the last three unpaired RNA nucleotides in the 39 flanking sequence followed by a much slower cleavage through the stem that occurs over a longer incubation period in the order of hours. ERI1-mediated RNA metabolism plays a key role in chondrogenesis.
Synonyms: HEXO; THEX1; 3'HEXO; HXAL; SEMDGC; SEMDGS
Tractability: Small molecule: a structure with a bound ligand is known; it has a binding pocket of medium quality. PROTAC: ubiquitination databases record sites on it; its protein half-life has been measured.
Gene: Protein-coding gene on chromosome 8 (9,002,147 to 9,116,746, forward strand). Ensembl gene ENSG00000104626.
Subcellular location: Cytoplasm; Nucleus; Nucleus, nucleolus
Subcellular location (Human Protein Atlas): Microtubules; Vesicles
Pathways (Reactome):
Metabolism of RNA: Major pathway of rRNA processing in the nucleolus and cytosol
Gene Ontology:
Molecular function: 3'-5' exonuclease activity; exoribonuclease II activity; protein binding; 3'-5'-RNA exonuclease activity; histone pre-mRNA stem-loop binding; ribosome binding; rRNA binding; nucleic acid binding
Biological process: histone mRNA catabolic process; maturation of 5.8S rRNA; exonucleolytic trimming to generate mature 3'-end of 5.8S rRNA from tricistronic rRNA transcript (SSU-rRNA, 5.8S rRNA, LSU-rRNA); negative regulation of regulatory ncRNA-mediated heterochromatin formation; rRNA 3'-end processing; rRNA processing
Cellular component: cytoplasm; nucleolus; nucleus; histone pre-mRNA 3'end processing complex
Genetic constraint (gnomAD): Loss-of-function variants: 18 observed, 17.45 expected, observed/expected ratio (o/e) 1.03, 90% interval 0.71 to 1.53. The synonymous counts are far from expectation, so gnomAD's model fits this gene poorly and the ratio says little. Missense variants: 388 observed, 275.56 expected, observed/expected ratio (o/e) 1.41, 90% interval 1.29 to 1.53. Synonymous variants: 131 observed, 97.73 expected, observed/expected ratio (o/e) 1.34, 90% interval 1.16 to 1.55.
Homologues: Orthologues: macaque ERI1 (96% identical), dog ERI1 (92% identical), rabbit ERI1 (91% identical), pig ERI1 (90% identical), guinea pig ERI1 (87% identical), rat Eri1 (85% identical), mouse Eri1 (83% identical), chimpanzee ERI1 (77% identical), tropical clawed frog eri1 (69% identical), zebrafish eri1 (59% identical), Caenorhabditis elegans eri-1 (32% identical), Caenorhabditis elegans crn-4 (17% identical). Paralogues in human: ERI3 (26% identical), ERI2 (24% identical).
Diseases named in the same sentence as ERI1 in open-access papers:
ERI1 is named in the same sentence as 22 diseases in open-access papers, as found by Europe PMC text mining. Sharing a sentence is not in itself a finding about the gene and the disease. The quoted sentences say what the papers report.
atherosclerosis (2 papers, 2021 to 2025). A disease characterized by the build-up of fatty material and calcium deposition in the arterial wall resulting in partial or complete occlusion of the arterial lumen. "Other notable genes included XKR6 (XK-related protein 6), implicated in apoptotic processes central to atherosclerosis, and ERI1 (exoribonuclease 1), which may influence vascular remodeling through RNA metabolism." (PMID 41299637, 2025). "TRIP6, PINX1, and ERI1 have notably been associated with blood pressure, triglyceride levels, HDL cholesterol, diabetes mellitus, and atherosclerosis." (PMID 34753499, 2021). "The gene-based association identified genes (TRIP6, PINX1 and ERI1) were significantly associated with expression change in the whole blood and lung and have previously been associated with blood pressure, triglyceride levels, HDL cholesterol, diabetes mellitus and atherosclerosis." (PMID 34753499, 2021).
dementia (2 papers, 2022 to 2023). Loss of intellectual abilities interfering with an individual's social and occupational functions. "In this RBPS, SMAD9 was found to be associated with dementia; POLR2F and ERI1 were identified to be associated with aging." (PMID 36118697, 2022). "A study reported that stroke was associated with cognitive impairment and dementia in older adults, and the six RNA-binding protein (RBP) genes (POLR2F, DYNC1H1, SMAD9, TRIM21, BRCA1, and ERI1) might participate in the process by mediating the hypoxic responses and angiogenesis." (PMID 37006557, 2023).
glioma (2 papers, 2022 to 2023). A benign or malignant brain and spinal cord tumor that arises from glial cells (astrocytes, oligodendrocytes, ependymal cells). "Lin established a 6-RBP gene signature consisting of POLR2F, DYNC1H1, SMAD9, TRIM21, BRCA1, and ERI1 in another bioinformatics work, allowing for a complete assessment of glioma and ischemic stroke." (PMID 37884559, 2023). "First, six prognostic-related RBP genes (POLR2F, DYNC1H1, SMAD9, TRIM21, BRCA1, and ERI1) were obtained from the TCGA-glioma dataset." (PMID 36118697, 2022). "The volcanic plot showed the differential analysis results of these six RBP genes, which showed that POLR2F and DYNC1H1 were downregulated in glioma, while TRIM21, BRCA1, ERI1, and SMAD9 were upregulated in glioma." (PMID 36118697, 2022). "Among them, POLR2F, DYNC1H1, and SMAD9 in tumor tissues of patients with glioma were downregulated as compared to normal tissues adjacent to cancer, while TRIM21, BRCA1, and ERI1 were upregulated." (PMID 36118697, 2022). "In all WHO grade II-IV gliomas, DNAss was positively correlated with the RBPS score, ERI1, BRCA1, and TRIM21, while negatively correlated with POLR2F, DYNC1H1, and SMAD9 [Spearman correlation, Benjamini-Hochberg (BH)-adjusted p < 0.05]." (PMID 36118697, 2022).
ovarian carcinoma (1 paper, 2021). A malignant neoplasm originating from the surface ovarian epithelium. "The roles of CYTH3 and ERI1 in ovarian cancer tumorigenesis have yet to be extensively explored in the literature." (PMID 34413360, 2021).
viral infection (1 paper, 2013). "Eri1-deficient NK cells also displayed decreased proliferation in response to MCMV infection, with increased viral titers, demonstrating the importance of Eri1 (probably due to miRNA alterations) in the context of viral infection." (PMID 23450173, 2013).
cancer (3 papers, 2021 to 2024). A tumor composed of atypical neoplastic, often pleomorphic cells that invade other tissues. "Although the essential role of ERI1 in miRNA biogenesis has been commonly reported, there are very few reports of ERI1 being associated with human diseases, including cancer." (PMID 38689093, 2024). "Using the Genomics of Drug Sensitivity in Cancer (GDSC) and The Cancer Genome Atlas (TCGA) databases, we identified 4 biomarkers (CYTH3, GALNT3, S100A14, and ERI1) to predict cisplatin sensitivity." (PMID 34676288, 2021).
tumor (3 papers, 2020 to 2025). "Next, we used the Tumor IMmune Estimation Resource (TIMER) to assess whether FGL2, ERI1 or WNT5B expression correlated with infiltrating immune cell levels in ESCA." (PMID 33323552, 2020). "However, ERI1 expression did not correlate significantly with ESCA tumor purity, and only correlated weakly with the infiltrating levels of B cells (r = 0.243, P = 10.4e-03), CD8+ T cells (r = 0.179, P = 1.59e-02) and DCs (r = -0.185, P = 1.28e-02)." (PMID 33323552, 2020).
ERI1 also shares sentences with these, for which no sentence is quoted: diabetes mellitus (2 papers); ischemic stroke (2); autoimmune disease (1); cardiovascular disease (1); Cognitive impairment (1); heart disease (1); Insulin resistance (1); Lupus (1); Obesity (1); rheumatic diseases (1); rheumatoid arthritis (1); scleroderma (1); Stroke (1); type 1 diabetes mellitus (1); type 2 diabetes mellitus (1).